HSF1 (heat shock transcription factor 1)
Diseases named in the same sentence as HSF1 in open-access papers (continued):
Sharing a sentence is not in itself a finding about the gene and the disease.
liver cancer (continued). "In addition, the finding that half of the examined HCC (32 of 64, 50%) display amplification of either c-Myc or HSF1 implies that this genetic event is a very frequent alteration in human liver cancer." (PMID 29207593, 2017). "Therefore, the present data strongly support an important prognostic role of HSF1 in human liver cancer." (PMID 28903330, 2017). "Nonetheless, we showed for the first time that HSF1 and c-Myc regulate each other’s levels, thus suggesting that HSF1 might suppress c-Myc dependent liver cancer development by directly acting on the c-Myc gene." (PMID 29207593, 2017). "In conclusion, HSF1 is an independent prognostic factor in liver cancer and might represent an innovative therapeutic target in HCC subsets characterized by activation of the AKT/mTOR pathway." (PMID 28903330, 2017). "Moreover, the impact of HSF1 on the proliferation of liver cancer cells was evaluated in vivo." (PMID 39248163, 2024). "In conclusion, these results demonstrated that HSF1 occupies both the promoter and SE regions of MYCN, thus activating its transcription in liver cancer cells." (PMID 39248163, 2024). "To determine the biological function of HSF1 in liver cancer cells, we first used CRISPR/Cas9 technology to suppress endogenous HSF1 expression in Huh7 and MHCC97L cells." (PMID 39248163, 2024). "The results indicated that HSF1 functions as a transcription factor and directly binds to the promoter and SE of MYCN in liver cancer cells." (PMID 39248163, 2024). "Mechanistically, our findings demonstrate that HSF1 transcriptionally activates MYCN expression by binding to its promoter and SE elements, thereby promoting liver cancer cell proliferation." (PMID 39248163, 2024). "Moreover, their findings demonstrated that HSF1 is bound to its promoter and SE elements to transcriptionally activate MYCN expression, thereby promoting liver cancer cell proliferation." (PMID 40606603, 2025). "Moreover, HBX directly activates the transcription factor HSF1 to upregulate the expression of HSPA8, inhibiting ferroptosis in liver cancer cells." (PMID 39532842, 2024). "The HSF1‐MYCN axis constitutes a transcription‐dependent regulatory mechanism that may function as both a prognostic indicator and a promising therapeutic target in liver cancer." (PMID 39248163, 2024). "In human liver cancer specimens, we detected that HSF1 is progressively induced from human non-tumorous surrounding livers to HCC, reaching the highest expression in the tumors characterized by the poorest outcome (as defined by the length of patients’ survival)." (PMID 28903330, 2017).
Parkinson disease (11 papers, 2014 to 2025). A progressive degenerative disorder of the central nervous system characterized by loss of dopamine producing neurons in the substantia nigra and the presence of Lewy bodies in the substantia nigra and locus coeruleus. "Intriguingly, LbGp also ameliorated neurodegenerative diseases such as Parkinson’s disease in a DAF-16-, SKN-1-, and HSF-1-dependent manner." (PMID 37469953, 2023).
triple-negative breast carcinoma (10 papers, 2012 to 2025). An invasive breast carcinoma which is negative for expression of estrogen receptor (ER), progesterone receptor (PR), and human epidermal growth factor receptor 2 (HER2). "HSF1 was identified to be more active in basal or triple-negative breast cancers, which have striking molecular similarities to HGSOC, and HSF1 was recently shown to be overexpressed and/or hyperactivated in HGSOC and other solid tumors." (PMID 39831777, 2025). "Elevated levels of HSF1 also positively correlate with invasive characteristics of triple-negative breast cancer cells." (PMID 37894333, 2023). "In summary, we report here that WA causes denaturation and proteasome-dependent degradation of HSF1 and BRCA1 proteins in MDA-MB-231 and BT20 triple-negative breast cancer cells." (PMID 25969759, 2012). "Moreover, HSF1 levels positively correlated with the invasive phenotype of triple-negative breast cancer cells, and their growth was inhibited by the HSF1 inhibitor DTHIB." (PMID 37894333, 2023). "Furthermore, we analyzed the effect of HSF1 on the phenotype of triple-negative breast cancer cells and found that increasing HSF1 levels positively correlated with the acquisition of an invasive phenotype in Matrigel." (PMID 37894333, 2023). "The purpose of this study was to examine the regulation of prosurvival factors heat shock factor 1 (HSF1) and breast cancer susceptibility gene 1 (BRCA1) by a natural withanolide withaferin A (WA) in triple negative breast cancer cell lines MDA-MB-231 and BT20." (PMID 25969759, 2012). "The fact that attenuated expression of HSF1 and BRCA1 proteins were associated with the apoptotic effects of WA in both MDA-MB-231 and BT20 cells suggests that they may play a role in the anticancer action of WA in triple negative breast cancer cell lines." (PMID 25969759, 2012). "When triple-negative breast cancer cells undergo RSR, the JNK-HSF1 signaling pathway is activated, then USP36 is transcriptionally activated by HSF1." (PMID 40909126, 2025). "In TNBC (triple negative breast cancer) cells, DYRK2 actively regulates the nuclear stability and activity of HSF1 by phosphorylation at ser320 and ser32618." (PMID 36104345, 2022). "Here we demonstrate that in triple-negative breast cancer (TNBC) cells, the dual specificity tyrosine-regulated kinase 2 (DYRK2) phosphorylates HSF1, promoting its nuclear stability and transcriptional activity." (PMID 33268814, 2021). "In the present study, we intended to examine the effects of WA on BRCA1 and HSF1 protein expression in MDA-MB-231 and BT20 triple-negative breast cancer cells as potential mechanisms of its anticancer action." (PMID 25969759, 2012). "We studied the HSF1 influence on the phenotype of non-tumorigenic human mammary epithelial (MCF10A and MCF12A) and several triple-negative breast cancer cell lines." (PMID 37894333, 2023).
viral infection (10 papers, 2005 to 2026). "Fever, nutritional deficiency, inflammation, oxidative stress and viral infection can activate the binding of HSF1 to HSE elements and induce HSP27, HSP70 and HSP90 expression." (PMID 35659731, 2022). "Although there is very little information regarding the effect that the modulation of HSF1 activity may have over viral infections, there are multiple connections between gene products associated with this transcription factor and viral infections." (PMID 35485710, 2022). "Viral infection leads to HSF1 activation and consequently an increase in the expression of HSP genes, such as members of the HSPA, DNAJ, and HSPC families, which support the assembly and release of viral particles." (PMID 40457168, 2025). "The impact of HSF1 on viral infections, including HIV‐1, was comprehensively described in a recent review." (PMID 40457168, 2025). "Here, we review aspects related to HSF1 activation and discuss what is known regarding the role of HSF1 during viral infections." (PMID 35485710, 2022). "Here, we review the role of HSF1 in different viral infections and its impact on the health outcome for the host." (PMID 35485710, 2022). "At present, most studies evaluating a role for HSF1 in viral infections are focused on the activation of this transcription factor during infection caused by the human immunodeficiency virus (HIV)." (PMID 35485710, 2022). "To differentiate between these options, we pharmacologically inhibited HSF1 activity coincident with virus infection, for acute inhibition of HSF1 activity." (PMID 24516381, 2014). "HSF1 is best known for its activation of transcription of the heat shock protein genes during proteotoxic stress, like heat, UV, and viral infections, but HSF1 also plays a physiological role in setting the circadian rhythm." (PMID 22797943, 2012). "Because fever frequently occurs upon viral infections, HSF1 activation may be common during viral infections, although this has not been studied extensively." (PMID 35485710, 2022). "Understanding the interplay between HSF1 and viral infections could help identify novel pharmacological targets for the development of antiviral therapeutic approaches." (PMID 35485710, 2022). "Thus, we foresee that targeting HSF1 will be an interesting new approach for the treatment of viral infections, given the constant need for identifying and developing new drugs to combat this type of pathogens." (PMID 35485710, 2022). "The small decrease in HSF1 content found by us on the third day p.i., might result from limited cellular protein synthesis observed during the prolonged viral infection." (PMID 16246258, 2005). "This is particularly surprising, given that a sudden increase in body temperature, such as might occur with fever is a frequent host response during viral infections, and thus, HSF1 may be activated under these circumstances and have an impact on the progression of the infections." (PMID 35485710, 2022). "Furthermore, it is unknown if HSF1 may have a potential as a new therapeutic target for different viral infections." (PMID 35485710, 2022). "Thus, it is possible to envisage that viral infections could modulate the action of enzymes that modify HSF1 in a post‐translational manner, in such a way to favor or inhibit its activation." (PMID 35485710, 2022). "Importantly, an accumulating body of studies relates HSF1 with viral infections; the induction of fever during viral infection may activate HSF1 and trigger a consequent heat shock response." (PMID 35485710, 2022). "Additionally, a role between HSF1 and viral infections has been described, although in a somewhat limited manner despite the fact that HSPs are known to participate in many processes related to viral infection, such as viral entry, viral replication, and viral gene expression, among others." (PMID 35485710, 2022).
viral infection (continued). "We further confirmed the importance of HSF1 for VACV replication by analyzing virus infection in knockout mouse embryonic fibroblasts (MEFs) lacking HSF1." (PMID 24516381, 2014). "In this study, we investigate the molecular mechanisms by which elevated temperatures confer resistance to viral infections, focusing on the role of heat shock factor 1 (HSF1) in regulating antimicrobial effectors rather than the traditional target genes molecular chaperones." (PMID 41989269, 2026). "These drugs have not been tested in the context of viral infection, yet they may have effects that limit viral progression through the inhibition of HSF1." (PMID 35485710, 2022).
bladder cancer (9 papers, 2013 to 2025). "The differential expression of HSPA1A in the four bladder cancer cell lines tested was associated with differential binding of HSF1 to the HSPA1A promoter, which was due to HSPA1A promoter methylation in the UM-UC10 and UM-UC13 cells." (PMID 23874968, 2013). "When bladder cancer cells were transfected with HSF1 plasmid, the apoptosis induced by silibinin was partially reversed." (PMID 38164275, 2024). "Western blotting and immunohistochemical staining results from tumor tissues demonstrated that silibinin suppressed bladder cancer growth through inhibiting HSF1/Hsp70 pathway." (PMID 38164275, 2024). "Taken together, our data indicates that silibinin induces mitochondrial apoptosis via inhibiting HSF1/Hsp70 pathway and also suggests the therapeutic potential of silibinin in the treatment of bladder cancer." (PMID 38164275, 2024). "Results from in vivo study demonstrated that silibinin suppressed the growth of bladder cancer xenografts, which was accompanied with the activation of caspase-3 and downregulation of HSF1 and Hsp70." (PMID 38164275, 2024). "Mechanically, HSF1/Hsp70-regulated mitochondrial apoptotic pathway is involved in silibinin-induced apoptosis in bladder cancer." (PMID 38164275, 2024). "HSF1 promotes multiple steps in the process of LN metastasis in bladder cancer through a novel PRMT5-WDR5-dependent transcriptional mechanism." (PMID 37783676, 2023). "First, Recent studies suggested that OICR-9429 and HSF1 played important roles in regulating the tumor microenvironment of bladder cancer." (PMID 36267410, 2022). "Expression of IER5 and cancer-associated HSF1 target genes (RBM23 and EIF4A2) showed a significant association in bladder cancer (r = 0.64 and p < 0.0001 for RBM23, and r = 0.54 and p < 0.0001 for EIF4A2)." (PMID 26754925, 2016). "Importantly, HSF1 was also found to promote lymphatic metastasis in bladder cancer via a PRMT5-WDR5-dependent transcriptional program." (PMID 40675964, 2025). "Overall, regardless of which isoform generates Hsp72 protein expression, our data show that suppression of Hsp72 induction enhances bortezomib sensitivity, and support the further development of HSF1 and Hsp72 inhibitors to increase bortezomib sensitivity in bladder cancers." (PMID 23874968, 2013). "Bladder cancer cells T24 and RT4 were treated with silibinin for 24 hours and 48 hours, and the expression of HSF1 was detected using western blotting." (PMID 38164275, 2024). "In this study, we investigated the effects of the aqueous extract of Cinnamon on human bladder carcinoma cell line 5637, especially on the gene expression of HSF1, ErbB2, and LDHA and the level of LDHA and HSF1 proteins and apoptosis." (PMID 35990198, 2022).
diabetes (9 papers, 2009 to 2025). "A comprehensive bioinformatics analysis showed that the T2D-associated polymorphisms of the HSF1 genes are linked with the changes in expression of genes involved in the unfolded protein response, a hallmark of the pathogenesis of type 2 diabetes mellitus." (PMID 36431071, 2022). "HSF1 is the key transcriptor controlling the transcription of iHSP, and decreased HSF1 expression in main metabolic tissues is highly associated with insulin resistance and diabetes." (PMID 29285313, 2017). "It is tempting to speculate that the HSF1-mediated increase in ECM proteins might be one mechanism to explain the thickening of the basement membrane in high glucose conditions associated with activated mTORC1, HSF1 and diabetes." (PMID 29247221, 2017). "Notably, the decreased transcriptional activity of HSF1 was found to enhance glucolipotoxicity-induced apoptosis in both rat and human β-cells, suggesting a role of heat shock factor 1 in the initial mechanisms underlying type 2 diabetes mellitus." (PMID 36431071, 2022). "Indeed, several reports showed that aging and progression of diabetes are both associated to malfunction and failure of the Hsf-1 system, suggesting loss of cell ability to respond to stress and increased susceptibility to cell damage in later stages of age-related diseases." (PMID 20885985, 2010). "Certain data in the literature indicate changes in the expression levels of HSF1 in type 2 diabetes mellitus." (PMID 36431071, 2022). "Overall, these findings together strongly suggested that HSF1 represents a novel therapeutical target for treating diabetes and other metabolic diseases." (PMID 29285313, 2017). "The use of N-terminal Hsp90 inhibitors in the alleviation of diabetes related symptoms has also been investigated due to the increased levels of insulin sensitivity observed upon HSF1 activation." (PMID 29247221, 2017). "Expression of HSF-1 decreases with age and diabetes and is induced by bDR, and hsf-1 RNAi completely blocks lifespan extension by bDR and the daf-2 mutation but does not block lifespan extension by other protocols of DR, nor predicts lifespan." (PMID 19924292, 2009). "Similarly, among genes whose expression was examined (including those previously implicated in mediating protective effects of DR), expression of only CBP, SATB-1, and HSF-1 decrease with age and diabetes." (PMID 19924292, 2009). "Similarly, cortical expression of CBP, SATB-1, and HSF-1 but not other genes implicated in influencing lifespan (e.g., the daf-16 ortholog FOXO3A) decreased with age and diabetes, a disease that mimics many effects of aging." (PMID 19924292, 2009).
heart failure (9 papers, 2016 to 2023). Inability of the heart to pump blood at an adequate rate to meet tissue metabolic requirements. "CHIP and HSF1 have both been reported to be associated with aging and oxidative stresses, which are considered the major contributors to aging and heart failure." (PMID 27809308, 2016). "However, the underlying mechanism by which HSF1 prevents cardiac fibrosis and inhibits heart failure remains unclear." (PMID 28091697, 2017). "Four weeks after TAC, when the expression of ALDH2 protein was downregulated, the effect of HSF1 in delaying heart failure weakened, and when ALDH2 was upregulated, the record was the contrary." (PMID 32626739, 2020). "We first established the pressure overload-induced heart failure model of mice by transverse aortic constriction (TAC) and discovered that, in the forming period of heart failure, changes of HSF1 and ALDH2 expression recorded the consistent trend." (PMID 32626739, 2020). "When HSF1 was upregulated/downregulated to delay/promote the occurrence of heart failure, PKC and ALDH2 also showed increased/decreased expression." (PMID 32626739, 2020). "Next, in the TAC 4-week heart failure model in vivo, we also observed that when HSF1 was upregulated, HSP90 and PKC recorded an increased expression, and when HSF1 was downregulated, the result was the contrary." (PMID 32626739, 2020). "And when ALDH2 was upregulated/downregulated, the role of HSF1 in delaying the occurrence of heart failure strengthened/weakened." (PMID 32626739, 2020). "In summary, through animal and cell experiments, we explored a novel mechanism for the occurrence and development of heart failure and demonstrated that HSF1 is the upstream regulating factor for ALDH2, and one of the mediators is PKC." (PMID 32626739, 2020). "Here, we demonstrated that anthocyanin acts as a cardioprotective drug against doxorubicin-induced heart failure by attenuating cardiac apoptosis via estrogen receptors to stabilize HSF1 expression and down-regulated IGF-IIR-induced cardiomyocyte apoptosis." (PMID 27657062, 2016). "Taken together, our findings indicate that CHIP coordinates with HSF1 to protect cardiomyocyte against apoptosis via direct interactions that increase HSF1 stability, which provides a novel strategy for preventing the progression of heart failure." (PMID 27809308, 2016). "Additionally, when ALDH2 in the heart of the HSF1 transgene mice was downregulated, the role of HSF1 in delaying the occurrence of heart failure weakened, and when ALDH2 was upregulated, the result was the contrary, when the expression of HSF1 increased, that of PKC also increased." (PMID 32626739, 2020). "To examine the role of ALDH2 in the cardioprotective effect of HSF1 in attenuating heart failure, we used the adenovirus transfection method to establish the ALDH2 upregulation/downregulation model of HSF1 transgene mice." (PMID 32626739, 2020). "We further used HSF1 transgene and knockout mice after TAC for 4 weeks and observed that HSF1 transgene mice recorded improved heart failure, which indicates that HSF1 probably plays its role in delaying the occurrence of heart failure via regulating ALDH2." (PMID 32626739, 2020). "But when heart failure occurred four weeks after TAC, HSF1 transgene mice recorded better heart function, and at the same time, the expression of ALDH2 mRNA and protein recorded increases." (PMID 32626739, 2020). "We discovered that, in the forming period of heart failure, HSF1 and ALDH2 recorded the consistent trend in terms of expression of their mRNA and protein, indicating that there exists a correlation between HSF1 and ALDH2." (PMID 32626739, 2020). "Therefore, our findings have significant implications for understanding heart failure and aging, and they expand our understanding of the indispensable protective role of CHIP and HSF1 in cardiomyocytes in response to stress." (PMID 27809308, 2016).